SMARCB1 (SWI/SNF related BAF chromatin remodeling complex subunit B1)
Diseases named in the same sentence as SMARCB1 in open-access papers (continued):
Sharing a sentence is not in itself a finding about the gene and the disease.
chordoma (continued). "Keywords associated with recent chemotherapy, PD-1-related immunotherapy, and SMARCB1/INI1 in chordoma were a shortage of research and there may be more research ideas in the future by scholars." (PMID 36520826, 2022). "The homozygous deletion of SMARCB1 is a hallmark of poorly differentiated chordoma, but this finding suggests that even partial inactivation of SMARCB1 in conventional chordoma could be used as a prognostic biomarker." (PMID 36248987, 2022). "Case analysis findings suggest that a SMARCB1 deletion is an early event in the rare traditional chordoma that may transform into PDC through supernumerary genome variation." (PMID 36520826, 2022). "The effect of SMARCB1 on chordoma cells was investigated in vitro and in vivo." (PMID 34668612, 2021). "To determine whether ATG5 participates in the tumour suppressor role of SMARCB1 in chordoma, we examined the effect of ATG5 knockdown in UM‐Chor1 and MUG‐Chor1 cells with SMARCB1 knockdown." (PMID 34668612, 2021). "Our results confirmed the tumour suppressor role of SMARCB1 in chordoma in vitro and in vivo." (PMID 34668612, 2021). "Here, we confirmed the tumour suppressor role of SMARCB1 in chordoma in vitro and in vivo." (PMID 34668612, 2021). "Here, we aim to explore the function and regulatory mechanisms of SMARCB1 in chordoma." (PMID 34668612, 2021). "We also investigated the effect of SMARCB1 on the migration and invasion of chordoma cells." (PMID 34668612, 2021). "Here, we examined the role and potential regulatory mechanism of SMARCB1 in chordoma." (PMID 34668612, 2021). "Our finding highlights that the SMARCB1/ATG5 axis is a promising therapeutic target for chordoma and autophagy inhibitors may be effective agents for chordoma treatment." (PMID 34668612, 2021). "Although the homozygous loss of SMARCB1 was not seen in our chordoma patients, patients with hemizygous 22q deletion showed reduced expression of SMARCB1 at the mRNA level." (PMID 33536423, 2021). "Our analysis revealed that both chordomas exhibited high CD8+ T cell expression signatures compared to several other paediatric and adult cancer data sets, including paediatric cranial and extra-cranial RTs that are similarly SMARCB1/INI1-deficient." (PMID 34931022, 2021). "Therefore, another phase II clinical trial on tazemetostat is ongoing in patients with SMARCB1/INI1 deleted chordoma (NCT02601950)." (PMID 30775316, 2019). "Therefore, in this case of a poorly differentiated chordoma, the loss of SMARCB1 expression was due to gene silencing rather than genomic loss of the gene locus, a mechanism already described for other poorly differentiated chordomas." (PMID 38786326, 2024). "In neoplasms with pleomorphic and/or rhabdoid morphology such as SMARCB1-deficient neoplasms, SMARCA4-deficient neoplasms, malignant SFT, and CCS, a diagnosis of large cell NEC was proposed, while a NET diagnosis was discussed in the chordoma case and two of the CCSs." (PMID 34350470, 2021). "Thus, we speculated that SMARCB1 may function via autophagy in chordoma, and we then explored the ATGs in cells with changes in SMARCB1 expression." (PMID 34668612, 2021). "However, the downstream mechanism of SMARCB1 in chordoma remains largely unclear." (PMID 34668612, 2021). "Alterations in the SMARCB1/INI1 expression pattern have been detected in many tumors, including chordomas." (PMID 39199581, 2024). "Our results are in favour of the speculation that compared with SMARCB1 positive chordoma, the autophagy is enhanced in SMARCB1 negative chordoma due to the loss of SMARCB1 and subsequently transcriptional activation of ATG5, contributing to the malignant phenotype and adverse survival." (PMID 34668612, 2021). "To confirm the tumour suppressive effect of SMARCB1 in chordoma in vivo, we established a xenograft model in BALB/c nude mice using MUG‐Chor1 cells with stable transfection of SMARCB1." (PMID 34668612, 2021).
chordoma (continued). "Albeit usually slow-growing, chordomas can be aggressive mostly depending on their invasive behaviour and according to different histotypes and molecular alterations, including TBXT duplication and SMARCB1 homozygous deletion." (PMID 36983607, 2023). "In conclusion, the partial loss of SMARCB1/INI1, secondary to heterozygous deletion and/or copy number gain of SMARCB1, can be identified by immunohistochemistry in a significant portion of conventional chordomas, and is not peculiar of aggressive cases." (PMID 37456229, 2023). "SMARCB1/INI1-negative PDC is a unique subset of chordomas with clinical, histopathological, and molecular specificity, rapid progression, and poor prognosis, and should not be confused with traditional chordomas." (PMID 36520826, 2022). "Although an efficient antitumoral activity of the anti-EZH2 tazemetostat has already been reported in one SMARCB1/INI1 negative chordoma, there are no data concerning anti-EZH2 drugs on PBRM1-mutated chordoma, which is one of the most common genetic type." (PMID 35326637, 2022). "Two small studies reported a lack of nuclear expression of INI1 (SMARCB1) in poorly differentiated chordoma." (PMID 34067530, 2021). "We then asked the potential downstream molecules mediated by SMARCB1 in chordoma cells by ChIP sequencing of UM‐Chor1 cells incubated with or without an anti‐SMARCB1 antibody." (PMID 34668612, 2021). "Taken together, our results revealed that the SMARCB1/ATG5 axis is a promising therapeutic target for chordoma and autophagy inhibitors may be effective agents for chordoma treatment." (PMID 34668612, 2021). "Further studies including metabonomics and phosphorylation proteomics of chordoma cells with SMARCB1 changes or SMARCB1 positive/negative chordoma are highly recommended to comprehensively analyse the mechanism of SMARCB1 in chordoma." (PMID 34668612, 2021). "Mechanistically, SMARCB1 binds directly to the ATG5 promoter and transcriptionally regulates its expression, which subsequently regulates autophagy and the malignant phenotype of chordoma." (PMID 34668612, 2021). "The “poorly differentiated chordoma” is an entity characterized by the absence of SMARCB1 (i.e., INI1) expression originated from the skull base and cervical spine." (PMID 32676456, 2020). "In other chordoma subtypes where SMARCB1 was downregulated but not lost, upregulation of microRNAs associated with transforming growth factor β signaling (TGF- β) was observed." (PMID 32733369, 2020). "Preserved SMARCB1 status in poorly differentiated chordoma is very rare but not unprecedented." (PMID 38786326, 2024). "Moreover, ChIP sequencing and GO analysis revealed that autophagy may be involved in the effect of SMARCB1 on chordoma cells and identified ATG5 as a novel transcriptional target of SMARCB1." (PMID 34668612, 2021). "Furthermore, unlike poorly differentiated chordoma and other types of carcinomas, log-rank test analysis showed no impact of SMARCB1/INI1 expression on overall and disease free-survival." (PMID 37456229, 2023). "Mechanically, explaining the molecular mechanism and potential role of transcriptional inhibition and immunologic responses to SMARCB1/INI1-negative PDC will be available for preclinical experiments and clinical trials and lead to new therapeutic opportunities for chordoma patients." (PMID 36520826, 2022).
synovial sarcoma (63 papers, 2013 to 2026). "The phase I study of tazemetostat, which targets the PRC2 catalytic subunit EZH2 (NCT02601937), included paediatric patients with relapsed or refractory RTs, other SMARCB1-deficient tumours, and synovial sarcoma." (PMID 40422882, 2025). "Preclinical studies have shown that CFT8634 is both potent and selective in degrading BRD9 in synovial sarcoma and SMARCB-1-deficient cases, demonstrating a DC50 value of 2.7 nM." (PMID 38675453, 2024). "On these grounds, BRD9 targeting using PROTAC degraders is currently under investigation in a phase 1 clinical trial (NCT04965753) in patients with advanced synovial sarcoma or advanced SMARCB1-loss tumors." (PMID 39261602, 2024). "Studies of ncBAF subunits as synthetic-lethal targets for synovial sarcoma and metastatic uveal melanoma are under way, as they share common SMARCB1 cBAF subunit mutations." (PMID 38914477, 2024). "This knowledge led to a clinical trial leveraging a BRD9 degrader in tumors with a loss of SMARCB1 in advanced synovial sarcoma and metastatic uveal melanoma (NCT04965753)." (PMID 38914477, 2024). "Studies have found that disruption of the ncBAF complex in samples with loss of SMARCB1 leads to attenuation of cell proliferation in synovial sarcoma." (PMID 36969064, 2023). "dBRD9 also altered transcriptional programmes essential for SMARCB1 loss-of-function driven tumours, thereby blocking proliferation of synovial sarcoma and MRT cells." (PMID 33941852, 2021). "Studies on RT and synovial sarcomas established that defects in SWI/SNF subunits SMARCB1 and SS18 cause cancer." (PMID 31123059, 2019). "In summary, the data presented in this work suggest that synovial sarcomas, like MRTs, are SMARCB1-deficient tumors that are sensitive to EZH2 inhibition." (PMID 27391784, 2016). "Furthermore, recent studies indicate that tumors deficient in SMARCB1, like synovial sarcoma and malignant rhabdoid tumors, exhibit a synthetic lethal dependency on BRD9." (PMID 38675453, 2024). "A phase I, open-label, dose escalation and expansion study is currently recruiting patients to evaluate the safety, tolerability, and preliminary clinical activity of FHD-609 for patients with advanced synovial sarcoma or advanced SMARCB1-loss tumors (ClinicalTrials.gov Identifier: NCT04965753)." (PMID 36969064, 2023). "Interestingly, synovial sarcoma is also defined by the loss of SMARCB1 protein levels when observed by immunohistochemistry." (PMID 35892904, 2022). "Loss of SMARCB1 activity is also a major driver for developing aggressive synovial sarcoma (SS)." (PMID 33941852, 2021). "Here we show that preclinical models of synovial sarcoma—a cancer characterized by functional SMARCB1 loss via its displacement from the SWI/SNF complex through the pathognomonic SS18-SSX fusion protein—display sensitivity to pharmacologic inhibition of EZH2, the catalytic subunit of PRC2." (PMID 27391784, 2016). "In this report, we investigate the potential that synovial sarcomas, due to their deficiency in SMARCB1, may be dependent on EZH2 activity." (PMID 27391784, 2016). "As the deficiency in SMARCB1 expression was the original hypothesis that led us to investigate the use of EZH2 inhibitors in synovial sarcoma, this may explain the differential sensitivity observed in this model." (PMID 27391784, 2016). "Thus, SMARCB1-deficient synovial sarcoma represents an additional indication which may display clinical response to EZH2 inhibition." (PMID 27391784, 2016). "Disruption of Arid1a or Arid1b (both CBAF-specific) retains synovial sarcoma character, while Smarcb1 (PBAF- and CBAF-specific) or Pbrm1 (PBAF-specific) disruption does not, although all accelerate SS18::SSX-driven tumorigenesis in mice." (PMID 41423472, 2025). "FHD-609, developed by Foghorn Therapeutics, Inc., was in a phase 1 trial (NCT04965753) in patients with advanced synovial sarcoma and SMARCB1-deleted tumors." (PMID 38543178, 2024).
synovial sarcoma (continued). "Increased BRD9 incorporation into the ncBAF complex has been reported in SMARCB1-mutated sarcoma cell lines and demonstrated to induce synthetic lethality in synovial sarcoma and rhabdomyosarcoma cell lines with perturbed SMARCB1." (PMID 39261602, 2024). "This suggests a post-transcriptional role for the degradation of SMARCB1 in the setting of synovial sarcoma." (PMID 35892904, 2022). "CFT8634 is an orally bioavailable degrader against BRD9 for the treatment of synovial sarcoma and SMARCB1-deleted solid malignancies." (PMID 36499765, 2022). "Other cancers with disrupted SMARCB1 function include synovial sarcoma (SS), myoepithelial carcinomas, and sinonasal carcinomas." (PMID 35892904, 2022). "While different mechanisms are at play with synovial sarcoma and MRTs, it demonstrates the important role that SMARCB1 plays in both polycomb antagonism and interactions with genomic targets." (PMID 32629987, 2020). "The best studied examples of how mutations of chromatin remodellers can cause malignancies are BAF47 (= SmarcB1) loss in rhabdoid tumours and the SS18-SSX fusion protein in synovial sarcoma." (PMID 30898143, 2019). "In MRT, SMARCB1 is lost due to biallelic inactivation of its gene, whereas in synovial sarcoma, SMARCB1 levels are lowered due to the presence of the SS18-SSX fusion protein." (PMID 27391784, 2016). "The SS18-SSX fusion in synovial sarcoma is known to disrupt the SWI/SNF assembly, resulting in SMARCB1-deficient complexes." (PMID 27783942, 2016). "SMARCB1 expression was quantified by densitometry and normalized to control β-actin levels, and found to be decreased in the synovial sarcoma cell lines relative to other sarcoma cell lines." (PMID 27391784, 2016). "Lastly, we examined expression of SMARCB1, which shows an altered expression pattern in the majority of synovial sarcomas." (PMID 27391784, 2016). "It has been reported that clinically 86% of synovial sarcoma tumors display low SMARCB1 expression, although the degree of expression varies across tumor specimens." (PMID 27391784, 2016). "The loss of SMARCB1 in these tumours may occur due to gene alterations, or in the case of synovial sarcoma, due to degradation of SMARCB1 protein by the SS18::SSX fusion transcript." (PMID 40983796, 2025). "Notably, a meta-analysis of synovial sarcoma, another neoplasm driven by deregulation of SMARCB1, revealed that high expression of p300 expression was associated with poor prognosis." (PMID 41290625, 2025). "Additionally, synovial sarcoma is characterized by a decreased level of SMARCB1 protein and high expression of SMARCB1 mRNA, which point to a post-transcriptional involvement in SMARCB1 degradation." (PMID 39313797, 2024). "One alteration this leads to is repression of SMARCB1, a cBAF complex protein that may act in tumor suppression and is found in ~70% of synovial sarcoma samples." (PMID 36969064, 2023). "A reduced expression of SMARCB1 has been reported for synovial sarcoma (SS)." (PMID 37093326, 2023). "Experimentally, inactivation of SMARCA4 potentiates lung adenocarcinoma and its metastasis, while displacement of SMARCB1 (BAF47), another key component of SWI/SNF complex, from SWI/SNF complex by SSX-SS18 fusion protein is associated with oncogenesis of synovial sarcoma." (PMID 37345003, 2023). "Finally, synovial sarcoma (SS) also shows reduced SMARCB1 function, following its eviction from the SWI/SNF complex subsequent to the incorporation of the hallmark SS18–SSX oncoprotein." (PMID 35327458, 2022). "However, synovial sarcoma samples with reduced SMARCB1 protein levels had high levels of SMARCB1 mRNA." (PMID 35892904, 2022). "The chemical probes I-BRD9 and BI-7273 both showed some weak cytotoxic effect in SMARCB1-deficient MRT and synovial sarcoma but, importantly, only at a relatively high compound concentration of about 10 μM or higher, hinting at off-target activity of these inhibitors at high concentration." (PMID 33941852, 2021).
synovial sarcoma (continued). "Mutations in MRTs consist of inactivating deletions or truncations of SMARCB1, and loss of SMARCB1 leads to a global decrease in its occupancy at enhancer and promoter regions as opposed to the relocalization seen in synovial sarcoma." (PMID 32629987, 2020). "We additionally observed sensitivity to EZH2 inhibition in a SMARCB1-deficient synovial sarcoma xenograft, but not a synovial sarcoma xenograft expressing wild-type levels of SMARCB1." (PMID 27391784, 2016). "Given the sensitivity of SMARCB1-deficient tumors to EZH2 inhibition, and the diminution of SMARCB1 levels observed in SS18-SSX translocation positive synovial sarcomas, we hypothesized that synovial sarcomas may be similarly dependent on PRC2/EZH2 activity." (PMID 27391784, 2016). "As such, we believe that the karyotype, unstable genotype, CD57 staining, and lack of SMARCB1-deficiency suggest that HS-SY-II is not a representative xenograft for SMARCB1-deficient synovial sarcoma." (PMID 27391784, 2016). "Loss of SMARCB1 is a major driver in aggressive synovial sarcoma (SS) based on the presence of a SS18-SSX fusion protein that prevents SMARCB1 interaction with BAF and PBAF." (PMID 39237495, 2024). "Furthermore, reduced SMARCB1 protein expression is found in a proportion of synovial sarcomas." (PMID 27783942, 2016). "Further studies are needed to explore the relationship between SMARCB1 expression and EZH2 dependence in synovial sarcoma." (PMID 27391784, 2016). "The study was followed by a phase II, multicenter study in adult subjects with SMARCB1/INI1-negative tumors or relapsed/refractory synovial sarcoma (NCT02601950) in 2015." (PMID 36078034, 2022). "However, a retargeting becomes evident in our data and has also been shown in data published on synovial sarcoma, a cancer entity in which BAF complexes contain an SS18-SSX fusion protein but also lose SMARCB1 in their complexes." (PMID 35456033, 2022). "Therefore, in both RT and synovial sarcoma, SMARCB1 is lacking from BAF (but not from PBAF)." (PMID 31123059, 2019). "We have previously shown that SMARCB1-negative MRT tumors are dependent on EZH2 activity, and we therefore investigated whether the synovial sarcoma cell lines, with decreased SMARCB1 expression, would likewise display a similar sensitivity to EZH2 inhibition." (PMID 27391784, 2016).